IL1B (interleukin 1 beta)
Diseases named in the same sentence as IL1B in open-access papers (continued):
Sharing a sentence is not in itself a finding about the gene and the disease.
Salmonella Infections (continued). "In our study, both CASP1 and IL1β genes were observed upregulated after Salmonella infection, while no significantly dysregulated miRNA were identified to play critical roles in regulation of these genes." (PMID 29391047, 2018). "This is thought to be manifest by Casp11-mediated killing of phagocytes and release of Salmonella, without IL-1B mediated recruitment of neutrophils to limit Salmonella infection." (PMID 23977202, 2013). "Treatment of iSCs with DMSO alongside Salmonella infection had no significant impact on the fold increases in IL1B mRNA expression by iSCs." (PMID 24137162, 2013). "In the current study, we found that IL-1β-/- mice do not succumb to Salmonella infection." (PMID 38236896, 2024). "However, Salmonella infection dramatically reduced the levels of Clostridia bacteria in infected WT mice while not affecting these microbes in IL-1β-/- mice." (PMID 38236896, 2024). "Thus, Salmonella infection does not lead to depletion of SCFA-producing Clostridia bacteria in IL-1β-/- mice." (PMID 38236896, 2024). "It is known that Salmonella infection induces the expression of inflammasomes such as NLRP3 (nucleotide-binding, oligomerization domain- (NOD-) like receptor family, pyrin domain containing 3) to release proinflammatory cytokines like IL-1β (interleukin 1 beta)." (PMID 36704315, 2023). "While the precise nature of this interaction is still a subject of debate, it has been suggested that the NAIP/NLRC4/ASC complex formed after Salmonella infection may recruit NLRP3, potentially amplifying caspase-1 cleavage and subsequent IL-1β cytokine release." (PMID 38124741, 2023). "The observed increase in the IL-1β and IFNγ mRNA of CD4+CD25- cells occurred only in the internal organ but not in the cecal tonsils, suggesting that the systemic host immune response to Salmonella infection differs from the mucosal immune response to Salmonella." (PMID 34843525, 2021). "We propose that IL-1β release without pyroptosis may occur in early-recruited monocytes to regulate a maximal innate immune response to Salmonella infection, allowing a sustained inflammatory signal." (PMID 28761045, 2017). "In Salmonella infection caspase-8 processes IL-1β but does not affect pyroptosis." (PMID 27670879, 2016). "Also, Salmonella infection of chicken macrophages led to significant increase in secretion of IL-1β to cell culture supernatant, while b-AP15 compound inhibited secretion of pro-IL-1β in Salmonella-infected cells, as quantified by chicken IL-1β ELISA assay." (PMID 26267804, 2015). "During Salmonella infection, caspase-8 can be recruited to the NLRC4 inflammasome regulating IL-1β secretion, but not playing a role in cell death." (PMID 36532444, 2022). "However, we observed a strongly augmented inflammatory signaling in FTH-deficient primary macrophages even without any bacterial or proinflammatory stimulus and Salmonella infection could drastically boost secretion of the inflammasome-dependent IL-1β in these cells." (PMID 34236052, 2021). "As observed for AIEC-LF82, in case of Salmonella infection the absence of either ELMO1 or NOD2 or both resulted in a delayed bacterial clearance and significant decline in levels of IL-6 and IL-1β compared to C1 cells." (PMID 36694274, 2023). "The results showed that GlcN not only inhibited NLRP3 inflammasome but also reduced IL-1β secretion in AIM2-, non-canonical- and NLRC4-inflammasome activated J774A.1 macrophages, which are stimulated by poly(dA:dT) and LPS transfection or by Salmonella infection, respectively." (PMID 30944389, 2019).
Peri-Implantitis (89 papers, 2014 to 2026). An inflammatory process with loss of supporting bone in the tissues surrounding functioning DENTAL IMPLANTS. "The subgroup of studies focusing on cytokine polymorphisms (IL-1A, IL-1B, IL-10, IL-17A) demonstrated variable associations with peri-implantitis risk." (PMID 41373620, 2025). "The results demonstrated that genotypes with the T allele in IL-1A-889C/T and IL-1B+3954C/T were significantly associated with an elevated risk of peri-implantitis and with more unfavorable clinical values." (PMID 41373620, 2025). "The ROC curves were used to evaluate the diagnostic ability of ET-1 and IL-1β for peri-implantitis and peri-implant mucositis, respectively." (PMID 38874661, 2024). "Regarding dental implants, a systematic review has reported that the central cytokines associated with peri-implantitis were IL-1β, IL-6, IL-17, TNF-α, RANK, and RANKL." (PMID 38614881, 2024). "Analysis of the association between IL-1B +3954 polymorphism and the risk of peri-implantitis in dominant and recessive genetic models." (PMID 38203822, 2024). "Further research has indicated that pro-inflammatory mediators associated with peri-implantitis include interleukin-1 beta (IL-1β), IL-6, IL-17, and tumor necrosis factor-alpha (TNF-α)." (PMID 39555067, 2024). "Although there is no consensus in the literature regarding the role of genetic polymorphisms in the development of peri-implantitis, most studies have focused on IL-1A -889, IL-1B +3954, and IL-1RN variable number of tandem repeats (VNTR) polymorphisms." (PMID 38203822, 2024). "It was found that there was a correlation between IL-1β +3953, together with IL-1α (−889), and an increased risk of peri-implantitis." (PMID 37232785, 2023). "After conducting this review, we found that only two authors demonstrated a significant association between the composite genotype of IL-1β (+ 3945) and IL-1α (− 889) and the presence of peri-implantitis." (PMID 35061134, 2022). "We aimed to investigate if individuals carrying the genetic single nucleotide polymorphism (SNP) in the IL-1A (rs1800587) and IL-1B (rs1143634) genes are more susceptible to develop peri-implantitis." (PMID 35855430, 2022). "The two most widely studied genetic variations, with respect to a possible relationship with peri-implantitis, are IL-1A-889T and IL-1B +3954T, which both have shown to be associated with changes in gene expression and protein secretion." (PMID 35855430, 2022). "In the present study, we aimed to investigate the possible association of IL-1A- 889T and IL-1B+ 3954T polymorphisms with the peri-implantitis in a Portuguese cohort." (PMID 35855430, 2022). "Allelic frequencies of polymorphisms of IL-1A-889 and IL-1B+3954 in the peri-implant health group and in the peri-implantitis group." (PMID 35855430, 2022). "Genotypic frequencies in polymorphisms of IL-1A-889 and IL-1B+3954, in the periimplant health group and in the peri-implantitis group." (PMID 35855430, 2022). "A recent meta-analysis found that carriers of positive genotype of IL-1A-889 and IL-1B+3954 had 1.95-fold risk of peri-implant disease (which included implant failure/loss, marginal bone loss and peri-implantitis)." (PMID 35855430, 2022). "Comparing both studies, for both IL-1A-889 and IL-1B+3954 polymorphisms, there is a higher percentage of T alleles in the peri-implantitis group and a higher percentage of C alleles in the health group." (PMID 35855430, 2022). "Genetic polymorphisms in IL1B are related to the risk of peri-implantitis and contribute to increased clinical parameters, such as peri-implant pocket depth, plaque index, and clinical attachment level." (PMID 34177950, 2021). "Results showed that clinically stable treatment outcomes of peri-implantitis are associated with lower levels of putative pathogens total bacterial load and with reduction of IL-1β, IL-6, and VEGF levels in PICF." (PMID 31817894, 2019).
Peri-Implantitis (continued). "On the other hand, a recent meta-analysis concluded there was evidence of genetic effect (composite genotype IL-1A and IL-1B) on risk for implant failure and peri-implantitis." (PMID 26449434, 2015). "The conclusion drawn from this analysis indicates that IL-1A and IL-1B single-nucleotide polymorphisms (SNPs) could function as genetic markers of predisposition to peri-implantitis in the present population." (PMID 41373620, 2025). "Peri-implantitis has been linked to elevated salivary concentrations of IL1β." (PMID 38691206, 2024). "IL-1β is one of the candidate biomarkers that has been identified as being strongly associated with an increase in immuno-infiltrating cells in soft tissue samples obtained from peri-implantitis sites." (PMID 38203822, 2024). "Another interleukin-1β polymorphism that influences peri-implantitis is IL-1β (−511)." (PMID 37232785, 2023). "In the future, it will be necessary to carry out more studies in this area, with larger samples, so that it is possible to identify and obtain results with greater accuracy and evidence regarding the relationship of polymorphisms of IL-1A-889 and IL-1B+3954 with the development of peri-implantitis." (PMID 35855430, 2022). "Additionally, these clinical indexes were also associated with cytokine levels in peri-implantitis in this study, which showed that IL-1β, IL-6, IL-17A, VEGF, CXCL2, and G-CSF had a positive correlation with these three clinical indexes." (PMID 36233685, 2022). "Thus, with the completion of the meta-analysis, it is observed that, in Caucasian European descendants, there is a significant association between the positive genotype IL-1A-889 and IL-1B +3954 with peri-implantitis." (PMID 35855430, 2022). "We hypothesize that individuals carrying the T allele in the IL-1A-889 and IL-1B +3954 genes are more susceptible to develop peri-implantitis in comparison with individuals that don’t have these polymorphisms." (PMID 35855430, 2022). "(2020) with a sample of 318 Chinese patients, the authors observed that subjects carrying the T allele of IL-1A -889 and IL-1B +3954 had a significant 2.27–2.47-fold and 1.9–1.99-fold increased risk of peri-implantitis, respectively, when using the CC genotype as reference." (PMID 35855430, 2022). "IL-1β concentration in the peri-implant crevicular fluid could have diagnostic potential in peri-implantitis as its concentration was ten-fold higher in diseased sites as compared to healthy implants." (PMID 34054959, 2021). "Similarly, to the natural dentition, IL1β + 3954C/T genetic polymorphisms were found to be associated with an increased risk of peri-implantitis." (PMID 33081038, 2020). "The inflammatory factor of IL-1β, proved to play a significant role in the onset and progression of peri-implantitis, has been used as the most important diagnostic and treatment biomarker of peri-implantitis." (PMID 31985779, 2020). "Similarly, in peri-implantitis, polymorphisms in cytokine- and matrix-related genes (such as IL-1β, IL-17A, and MMP-8) may exert comparable regulatory effects on gene expression, contributing to dysregulated inflammation and tissue destruction." (PMID 41373620, 2025). "The development of easier diagnostic procedures and protocols may allow for better and cheaper diagnostics, especially for mixed IL-1α/IL-1β genotypes, thus allowing for the “tailor made” treatment of peri-implantitis and the early screening and maintenance of high-risk patients." (PMID 37232785, 2023). "As a typical pro-inflammatory cytokine, IL-1β is involved in immune regulation, affects connective tissue metabolism, causes inflammation, stimulates the creation and maturation of osteoclasts, and inhibits bone formation in peri-implantitis by triggering osteolysis." (PMID 36768193, 2023). "Consequently, the IL-1β cytokine is implicated in the resorption of bone and peri-implantitis." (PMID 37511404, 2023).
Peri-Implantitis (continued). "However, individuals with the C/C genotype of the SNP IL-1β (− 511) and those with composite genotype IL1β (+ 3945) and IL-1α (− 889) may have a higher risk for peri-implantitis." (PMID 35061134, 2022). "In univariate logistic regression analyses, both IL-1β and IL-6 were suggested as potential predictors of peri-implant mucositis and peri-implantitis (all p < 0.05)." (PMID 41877785, 2026). "La Monaca et al10 conducted a study on biomarkers in peri-implant crevicular fluid, identifying cortisol as one of the key indicators with predictive value for peri-implantitis, alongside IL-1β, VEGF, and sRANKL/OPG." (PMID 41399637, 2025). "Pro-inflammatory cytokine antagonists can effectively block the inflammatory response and bone resorption process of peri-implantitis by specifically inhibiting the activity of key inflammatory mediators such as IL-1β and tumor necrosis factor-α." (PMID 40851867, 2025). "IL-1β +3954 C/T, ET-1 and IL-1β, MMP-8 rs11225395 (T allele), MMP8 (−799 C/T), and CD14 rs2569190 showed consistent associations with increased peri-implantitis risk, while the results for TNF-α −308 G/A were inconsistent across populations." (PMID 41373620, 2025). "In peri-implantitis, IL-6, IL-1β, TNF-α, MMP-8, and their genetic variations appear to be the most important cytokines not only in pathogenesis but also in their potential diagnostic capabilities." (PMID 41172495, 2025). "The purpose of this study was to ascertain if ET-1 and IL-1β are utilized as an early indicator for peri-implantmucositis (PM) and peri-implantitis (PI), as well as to look into the relationship between ET-1 and IL-1β levels and peri-implantillnesses." (PMID 39917223, 2024). "Proinflammatory cytokines including TNF-α and IL-1β were statistically greater in peri-implantitis compared to peri-implant tissue in health." (PMID 39195095, 2024). "Genotype frequencies of IL-1A -889, IL-1B +3954, and IL-1RN (VNTR) polymorphisms, in the peri-implant health group, in the peri-implantitis group, and in the total sample." (PMID 38203822, 2024). "Higher levels of proinflammatory cytokines (interleukin (IL)-1β and IL-6) were observed in individuals with peri-implantitis compared to healthy implants." (PMID 38541894, 2024). "In the group of peri-implantitis who had a high score in stress level assessment scales, significantly higher IL-1β, IL-6, sAA expression levels were observed (p < 0.001)." (PMID 38691206, 2024). "Studies indicate that biomarkers like Matrix metalloproteinase 8 (MMP-8) and Interleukin1β (IL-1β) can be helpful in detecting peri-implantitis in the peri-implant sulcus fluid (PISF)." (PMID 39917223, 2024). "B cells significantly elevated in peri-implantitis lesions, accompanied by significantly increased levels of IL-1β, TNF-α, IL-4, and basic fibroblast growth factor." (PMID 39555067, 2024). "Observe the effects of treatment on clinical parameters indicative of mucositis or peri-implantitis (Δ PD; Δ PI; Δ BoP) and/or immunological parameters (Δ IL-1β; Δ IL-6; Δ IL-8; TNF-α)." (PMID 38686378, 2024). "Investigating cytokine levels in PICF revealed that IL-1β and MMP-9 levels tended to be the highest in the high-risk group, suggesting that the development of peri-implantitis converges from innate immunity to specific immunity." (PMID 39555067, 2024). "Specific immunity in peri-implantitis is characterized by elevated levels of pro-inflammatory cytokines such as IL-1β, IL-6, IL-17, and TNF-α, secreted by activated T cells and other immune cells." (PMID 39555067, 2024). "IL-1β levels in the peri-implantitis group were significantly higher than those in the healthy group (p < 0.01)." (PMID 38874661, 2024). "Supporting our results, there have been previous studies in which the pro-inflammatory cytokines IL-17 and IL-1β were detected higher in peri-implantitis compared to peri-implant health." (PMID 39080143, 2024).
Peri-Implantitis (continued). "Proinflammatory cytokines including TNF-α and IL-1β were significantly elevated in peri-implantitis." (PMID 39195095, 2024). "Comparing mucositis and peri-implantitis, three studies showed higher IL-1β levels and lower levels of IL-10 in peri-implantitis individuals." (PMID 37355561, 2023). "One study showed higher IL-1β levels and lower levels of IL-10 in individuals with mucositis and peri-implantitis in comparison to healthy." (PMID 37355561, 2023). "IL-1β also shows more intensified secretion in the early stages of peri-implantitis, triggering catabolic changes in a very early stage." (PMID 37232785, 2023). "IL-1β levels in peri-implantitis are elevated from the very beginning; hence, it can be used for diagnostic purposes before clinical manifestations." (PMID 37232785, 2023). "As inflammatory biomarkers, the variations of IL-1β, IL-6, and TNF-α are the most commonly studied functional polymorphisms for peri-implantitis and peri-implant bone loss." (PMID 36643585, 2023). "In the same study, the matrix metalloproteinase‐8 (MMP-8) demonstrated a trend similar to IL-1β, elevated in peri-implantitis and correlated with clinical parameters, such as bleeding on probing and increased probing depth." (PMID 36997949, 2023). "Otherwise, a systematic review concluded that the IL-1β, IL-6, IL-17, and TNF-α were the most frequently reported pro-inflammatory mediators associated with peri-implantitis." (PMID 36233685, 2022). "In a total of 13 studies included, only four of these presented sufficient data regarding the relationship between genotype positive IL-1A-889 and IL-1B+3954 and peri-implantitis." (PMID 35855430, 2022). "The link of SNP IL-1β (− 511) and peri-implantitis has been analyzed in four studies, but only two conducted in Japan recognized a direct relation to peri-implant bone loss." (PMID 35061134, 2022). "Studies have shown that the expression level of IL-1β at peri-implantitis sites was significantly higher than healthy implant sites." (PMID 35581339, 2022). "The close association of the four genetic variants IL-1a, IL-1b, TNF-a and IL-1RN with the risk of peri-implantitis development or implant loss has been demonstrated in a large number of worldwide association studies and was also confirmed in meta-analyses." (PMID 35819566, 2022). "The genera of Peptostreptococcaceae XIG-1, Treponema, Porphyromonas, and Lachnospiraceae G-8, as well as the cytokines of IL-17A, IL-6, IL-15, G-CSF, RANTES, and IL-1β were significantly higher in peri-implantitis than healthy implants." (PMID 36233685, 2022). "In accordance with the field of chronic periodontitis, the pro-inflammatory cytokines of the interleukin-1 (IL-1) cluster (IL-1a, IL-1b) are currently the most frequently analyzed factors in peri-implantitis." (PMID 35819566, 2022). "In patients with peri-implant mucositis, increasing peri-implant PD and IL-1β levels directly correlated with increased PISF suPAR (p < 0.001) and galectin-1 (p < 0.05) levels." (PMID 34585876, 2021). "It has been shown that the levels of TNF-α and IL-1β in PICF were positively correlated associated with peri-implant mucositis and peri-implantitis." (PMID 34429083, 2021). "Wang et al22 reported that the IL-1β levels in a healthy implant were significantly lower than in peri-implantitis." (PMID 35919677, 2021). "Apart from clinical and microbiological factors, future research should also focus on inflammatory markers such as IL-1β, IL-6 and IL-8 to identify the benefit of use of probiotics in the treatment of peri-implantitis." (PMID 34412595, 2021). "PICF level of IL-1β was significantly elevated in peri-implantitis sites than in healthy implant sites." (PMID 34610045, 2021). "Based on their results, there was no clear evidence to support the use of salivary biomarkers (IL-6, IL-1β) in peri-implantitis detection." (PMID 32349296, 2020).